TUBB2B (tubulin beta 2B class IIb)
Description:
Tubulin is the major constituent of microtubules, a cylinder consisting of laterally associated linear protofilaments composed of alpha- and beta-tubulin heterodimers. Microtubules grow by the addition of GTP-tubulin dimers to the microtubule end, where a stabilizing cap forms. Below the cap, tubulin dimers are in GDP-bound state, owing to GTPase activity of alpha-tubulin. Plays a critical role in proper axon guidance in both central and peripheral axon tracts. Implicated in neuronal migration.
Synonyms: MGC8685; DKFZp566F223; bA506K6.1; CDCBM7; PMGYSA
Tractability: Small molecule: an approved drug acts on it; a structure with a bound ligand is known; a high-quality ligand is known; it belongs to a druggable protein family. PROTAC: UniProt records ubiquitination sites on it; ubiquitination databases record sites on it; its protein half-life has been measured; a small molecule that binds it is known. Other modalities: an approved drug acts on it.
Target class: Structural protein
Gene: Protein-coding gene on chromosome 6 (3,223,324 to 3,231,730, reverse strand). Ensembl gene ENSG00000137285.
Subcellular location: Cytoplasm, cytoskeleton
Subcellular location (Human Protein Atlas): Microtubules; Basal body; Cytokinetic bridge; End piece; Flagellar centriole; Mitotic spindle; Primary cilium; Primary cilium tip; Principal piece
Pathways (Reactome):
Cell Cycle: EML4 and NUDC in mitotic spindle formation; Mitotic Prometaphase; Recruitment of NuMA to mitotic centrosomes; Resolution of Sister Chromatid Cohesion; Sealing of the nuclear envelope (NE) by ESCRT-III; Separation of Sister Chromatids; The role of GTSE1 in G2/M progression after G2 checkpoint
Vesicle-mediated transport: COPI-dependent Golgi-to-ER retrograde traffic; COPI-independent Golgi-to-ER retrograde traffic; COPI-mediated anterograde transport; Gap junction assembly; Microtubule-dependent trafficking of connexons from Golgi to the plasma membrane; Translocation of SLC2A4 (GLUT4) to the plasma membrane
Metabolism of proteins: Carboxyterminal post-translational modifications of tubulin; Formation of tubulin folding intermediates by CCT/TriC; Post-chaperonin tubulin folding pathway; Prefoldin mediated transfer of substrate to CCT/TriC
Signal Transduction: Hedgehog 'off' state; RHO GTPases Activate Formins; RHO GTPases activate IQGAPs
Immune System: MHC class II antigen presentation; PKR-mediated signaling
Neuronal System: Activation of AMPK downstream of NMDARs; Assembly and cell surface presentation of NMDA receptors
Organelle biogenesis and maintenance: Cargo trafficking to the periciliary membrane; Intraflagellar transport
Autophagy: Aggrephagy
Cellular responses to stimuli: HSP90 chaperone cycle for steroid hormone receptors (SHR) in the presence of ligand
Developmental Biology: Recycling pathway of L1
Disease: HCMV Early Events
Hemostasis: Kinesins
Gene Ontology:
Molecular function: protein binding; protein heterodimerization activity; GTP binding; structural constituent of cytoskeleton; GTPase activity
Biological process: microtubule-based process; neuron migration; positive regulation of axon guidance; mitotic cell cycle; cytoskeleton organization
Cellular component: ciliary tip; cilium; intercellular bridge; microtubule; microtubule cytoskeleton; mitotic spindle; nucleus; sperm end piece; sperm principal piece; cytoskeleton
Genetic constraint (gnomAD): Loss-of-function variants: 5 observed, 31.1 expected, observed/expected ratio (o/e) 0.16, 90% interval 0.083 to 0.34. The synonymous counts are far from expectation, so gnomAD's model fits this gene poorly and the ratio says little. Missense variants: 55 observed, 468.24 expected, observed/expected ratio (o/e) 0.12, 90% interval 0.094 to 0.15. Synonymous variants: 137 observed, 180.25 expected, observed/expected ratio (o/e) 0.76, 90% interval 0.66 to 0.88.
Gene-disease validity (ClinGen):
ClinGen rates the evidence that TUBB2B causes each of these diseases.
complex cortical dysplasia with other brain malformations (autosomal dominant): Definitive.
Homologues: Orthologues: dog TUBB2B (100% identical), guinea pig TUBB2B (100% identical), macaque TUBB2B (100% identical), mouse Tubb2b (100% identical), pig TUBB2B (100% identical), tropical clawed frog tubb2b (96% identical), zebrafish tubb2 (96% identical), Drosophila melanogaster betaTub85D (95% identical). Paralogues in human: TUBB2A (99% identical), TUBB4B (97% identical), TUBB (96% identical), TUBB4A (96% identical), TUBB3 (92% identical), TUBB6 (91% identical), TUBB8 (89% identical), TUBB8B (87% identical), TUBB1 (80% identical), TUBA1B (43% identical), TUBA1A (42% identical), TUBA1C (42% identical), and 11 more.
Diseases named in the same sentence as TUBB2B in open-access papers:
TUBB2B is named in the same sentence as 73 diseases in open-access papers, as found by Europe PMC text mining. Sharing a sentence is not in itself a finding about the gene and the disease. The quoted sentences say what the papers report.
polymicrogyria (19 papers, 2013 to 2025). A developmental brain abnormality characterized by an excessive amount of small convolutions on the surface of the brain and cognitive dysfunction. "Pathogenic heterozygous variants in TUBB2B have been associated with a range of neurodevelopmental disorders, with phenotypes including polymicrogyria and corpus callosum abnormalities." (PMID 41503485, 2025). "Consistent with its essential roles in neuronal migration and development, loss of TUBB2B has been implicated in rare forms of congenital neuronal disorders, including polymicrogyria, microcephaly and axon guidance defects." (PMID 39962586, 2025). "TUBB2B encodes a beta tubulin protein that is mutated in polymicrogyria, a cortical development disorder." (PMID 38714739, 2024). "A TUBB2B F265L mutation that causes multifocal polymicrogyria, has been shown to disrupt binding of the yeast homologue of EB1 known as Bim1." (PMID 36875768, 2023). "TUBB2B’s has been implicated in polymicrogyria, a condition, characterized by increased folding of cerebral cortex and cortical layer malformations." (PMID 37486945, 2023). "Most of the TUBB2B mutations related to polymicrogyria impair the ability to form functional α/β-tubulin heterodimers." (PMID 36769099, 2023). "D417N has also been reported in TUBB2B (causing polymicrogyria) and TUBB8 (causing oocyte maturation defect)." (PMID 37600020, 2023). "TUBB2B is a critical component of microtubules, and mutations in human TUBB2B result in polymicrogyria." (PMID 29716548, 2018). "Cases with tubulin related polymicrogyria-like cortical dysplasia carried mainly TUBB2B mutations (3/6), of which two were novel (p.P173L and p.A248T) and one was the seminal foetal case (p.S172P)." (PMID 25059107, 2014). "Conversely, TUBB2B mutations are responsible for either polymicrogyria (4/6) or microlissencephaly (2/6)." (PMID 25059107, 2014). "In addition to detecting pathogenic variants in genes previously linked to polymicrogyria (eg, ADGRG1/GPR56, SCN3A, TUBB2B), we discovered 6 genes linked to polymicrogyria for the first time (QRICH1, TMEM161B, PANX1, KIF26A, SCN2A, and MAN2C1)." (PMID 37486637, 2023). "R380C has also been reported in TUBB2B (causing perisylvian polymicrogyria)." (PMID 37600020, 2023). "Notably, mutation of the Tubb2b and Map1b genes have been implicated in polymicrogyria in the cerebral cortex." (PMID 34588434, 2021). "By contrast, TUBB2B mutations mostly account for generalized or multifocal polymicrogyria." (PMID 25059107, 2014). "A spectrum of neurological disorders (e.g. Polymicrogyria) characterized by abnormal neuronal migration, differentiation, organization, axon guidance, and maintenance has recently been associated with various mutations in Tubb2b." (PMID 23874995, 2013). "Finally, we deeply characterized one validated rSNP, demonstrating that it resides in a SOX10-responsive CRE that may regulate Tubb2b, which is mutated in patients with asymmetric polymicrogyria." (PMID 29716548, 2018). "Of note, a second substitution at this same residue in TUBB2B, TUBB2B E421K, was reported in a dominant family with CFEOM and polymicrogyria and, in yeast, the variant stabilized microtubules and reduced kinesin localization on microtubules." (PMID 37600020, 2023). "That said, TUBB3-MCD variants are reported to cause a spectrum of cortical malformations, including simplified gyral patterns, dysgyria, polymicrogyria, and lissencephaly but which are, overall, less severe than MCDs resulting from TUBA1A or TUBB2B variants." (PMID 37600020, 2023). "For instance, a E421K mutation in TUBB2B and a R262C mutation in TUBB3 both cause ocular motor dysfunction, whereas individuals with a T312M variant in TUBB2B and a R46G mutation in TUBB3 both present with multifocal polymicrogyria." (PMID 36875768, 2023).
polymicrogyria (continued). "Polymicrogyria (PMG) and polymicrogyria-like cortical dysplasia (PMG-like CD) were significantly more frequent in individuals of the TUBB2B cohort (P = 0.001 and P < 0.001, respectively)." (PMID 33082561, 2021). "Polymicrogyria or polymicrogyria-like cortical dysplasia and a simplified gyral pattern, which is common in TUBB2B and TUBB3 variants, have not been described in patients with TUBG1 variants so far." (PMID 29706637, 2018). "Concordant with prior literature, the most common genetic etiologies we found for polymicrogyria were in the PIK3R2 (9 families) and TUBB2B (6 families) genes." (PMID 37486637, 2023). "This includes lissencephaly (TUBA1A), polymicrogyria (TUBA1A, TUBB2B, TUBB3), microcephaly (TUBB2B, TUBB3, TUBB5, TUBG1), and oculomotor disorders (TUBB2B, TUBB3)." (PMID 33137126, 2020). "The association between microcephaly, polymicrogyria and cerebellar agenesis prompted us to screen for tubulin genes (TUBA1A, TUBA8, TUBB2A, TUBB2B, TUBB3, TUBB4A, TUBB, TUBG1), which were all negative." (PMID 35162247, 2022).
tubulinopathies (15 papers, 2014 to 2025). "TUBB2A, a neuron-specific beta-tubulin isotype with 90% homology to TUBB2B, is also associated with tubulinopathies." (PMID 41503485, 2025). "In this study, we report five individuals from four unrelated families with pathogenic TUBB2B variants, each contributing to an expanded allelic and phenotypic spectrum associated with TUBB2B-related tubulinopathies." (PMID 41503485, 2025). "Diagnostic delay was significantly higher in TUBB2B (12.3 years) compared with TUBA1A tubulinopathy (4.2 years)." (PMID 33082561, 2021). "Defined data on estimated survival, diagnostic delay, and disease characteristics of TUBA1A and TUBB2B tubulinopathy will help to raise disease awareness and encourage future clinical trials to optimize genetic testing, family counseling, and supportive care." (PMID 33082561, 2021). "We could show that particular malformations of cortical (lissencephaly, agyria) and extracortical (complete agenesis of the CC, brainstem hypoplasia) brain structures were associated with epilepsy in TUBA1A and TUBB2B tubulinopathies, respectively." (PMID 33082561, 2021). "Brain MRI showed diffuse corpus callosum hypoplasia, consistent with TUBB2B-related tubulinopathies." (PMID 41503485, 2025). "Brain MRI showed corpus callosum agenesis and cerebral atrophy, consistent with TUBB2B-related tubulinopathies." (PMID 41503485, 2025). "Mutations in seven genes encoding α- (TUBA1A), β- (TUBB2A, TUBB2B, TUBB3, TUBB4A, TUBB5), and γ- (TUBG1) microtubulin are linked to extensive overlapping brain malformations or tubulinopathies." (PMID 40948494, 2025). "The deletions of all individuals with a Dandy–Walker malformation/variant also included the gene TUBB2B (tubulin, beta-2b MIM*612,850) known to cause tubulinopathies when haploinsufficient." (PMID 36964621, 2023). "This condition is predominantly associated with TUBB2B mutations and to a small set of TUBB3 substitution, among tubulinopathies." (PMID 36769099, 2023). "Quantitative natural history modeling of individuals with TUBA1A and TUBB2B tubulinopathies from clinical reports and database entries of DECIPHER and ClinVar." (PMID 33082561, 2021). "TUBA1A and TUBB2B tubulinopathies usually become symptomatic in infancy at an average age of 4 and 6 months, respectively, but a considerable diagnostic delay of 4.2 and 12.3 years is observed until a genetic diagnosis is established." (PMID 33082561, 2021). "In return, TUBB2B tubulinopathy showed significant differences concerning the occurrence of basal ganglia (63.6% vs. 84.6%; P = 0.02) and ventricular dysgenesis, especially ventriculomegaly (44.3% vs. 88.0%; P < 0.001)." (PMID 33082561, 2021). "In this present study, we define the important primary endpoints survival, disease onset, and diagnostic delay analyzing the so-far largest quantitative analysis cohort of patients with TUBA1A and TUBB2B tubulinopathy." (PMID 33082561, 2021). "We quantitatively and comparatively delineate the natural history of TUBA1A and TUBB2B tubulinopathies by assessment of a large meta-cohort of 203 patients and provide their distinctive clinical features." (PMID 33082561, 2021). "TUBA1A and TUBB2B tubulinopathies are rare neurodevelopmental disorders characterized by cortical and extracortical malformations and heterogenic phenotypes." (PMID 33082561, 2021). "From 47 cases with TUBB2B tubulinopathy, 40 individuals (85.1%) were delivered at term and TOP was induced in 7 cases (14.9%) on average in GW 28 (range: GW 16–33)." (PMID 33082561, 2021). "During the course of disease, motor impairment, developmental delay, abnormalities of the muscular tone, microcephaly, and epilepsy were the most frequent clinical features but differed in distribution between individuals with TUBA1A and TUBB2B tubulinopathy." (PMID 33082561, 2021).
tubulinopathies (continued). "In comparison, patients with TUBB2B tubulinopathy show developmental delay at disease onset and are characterized by isolated learning difficulties and congenital fibrosis of the extraocular muscles." (PMID 33082561, 2021). "Epilepsy is a cardinal feature at disease onset of TUBA1A and TUBB2B tubulinopathy: 65.9% and 54.8% of patients, respectively, developed seizures during the observation period." (PMID 33082561, 2021). "Lissencephaly (32.8% vs. 6.8%) with pachygyria and/or agyria was a distinctive cortical finding in TUBA1A compared with TUBB2B tubulinopathy (P < 0.001)." (PMID 33082561, 2021). "We also report panhypopituitarism in Case 1, a feature not previously linked to TUBB2B tubulinopathies." (PMID 41503485, 2025). "Especially individuals with TUBB2B tubulinopathy were diagnosed late in childhood." (PMID 33082561, 2021). "Sanger sequencing of TUBB2B could be considered in undiagnosed patients with an MCD pattern highly suggestive of a tubulinopathy." (PMID 32895508, 2020). "Moreover, we sharpen the phenotypic profile of TUBA1A and TUBB2B tubulinopathy by comprehensively delineating isotype-dependent characteristics at disease onset and in the course of disease as well as neuroradiological features associated with epilepsy and an unfavorable clinical outcome." (PMID 33082561, 2021). "In the TUBB2B cohort, heterotopic neurons (83.3%), enlarged germinal zones (66.7%), and neuroglial overmigration (50.0%) were described, with neuroglial overmigration being a distinctive histopathological feature in TUBB2B tubulinopathy (9.5% vs. 50.0%; P = 0.024)." (PMID 33082561, 2021). "However, neither loss of Tubb2a nor Tubb2b results in the severe cortical malformations seen in the most common tubulinopathy patients." (PMID 31386652, 2019). "Other “tubulinopathies” genes include TUBA1A, TUBB2A, TUBB2B, TUBA8, TUBB3, TUBB, and TUBG1, which were found to be DEGAs in various brain regions." (PMID 34638726, 2021). "We identified a TUBB6 p.(Glu410Lys) variant in syndromic familial ptosis pedigree ENG_CML; this substitution has been reported as P/LP for tubulinopathies in four paralogs (TUBB2A, TUBB2B, TUBB3, and TUBB4A; ClinVar Variation IDs: 986830, 1195195, 6967, 135658)." (PMID 38585811, 2024). "In recent years, an increasing number of tubulin genes were linked to a clinically heterogeneous group of disorders, the “tubulinopathies” (TUBA1A, MIM#602529; TUBA8, MIM#605742; TUBB2A, MIM#615101; TUBB2B, MIM#612850; TUBB3, MIM#602661; TUBB, MIM#191130; TUBG1, MIM#191135)." (PMID 30744660, 2019).
Lissencephaly (8 papers, 2014 to 2023). A spectrum of malformations of cortical development caused by insufficient neuronal migration that subsumes the terms agyria, pachygyria and subcortical band heterotopia. "Regarding the role played by genetic alterations of the various genes involved in the determination of microtubule structure and function, TUBB2B gene mutations have been associated with various types of lissencephaly and axon dysinnervation." (PMID 29109381, 2017). "All foetuses with lissencephaly and cerebellar hypoplasia carried distinct TUBA1A mutations, while those with classical lissencephaly harbored recurrent mutations in TUBA1A (3 cases) or TUBB2B (1 case)." (PMID 25059107, 2014). "Only one patient with classical lissencephaly (LIS_TUB_013_ fœtus14) carried a TUBB2B mutation (p.G98R)." (PMID 25059107, 2014). "These neuronal overmigrations which represent the hallmark of type II (cobblestone) lissencephaly and were initially described as focal when associated with TUBB2B mutations are also a significant feature of tubulin related polymicrogyria and microlissencephaly." (PMID 25059107, 2014).
microcephaly (7 papers, 2017 to 2025). A congenital or acquired developmental disorder in which the circumference of the head is smaller than normal for the person's age and sex. "Microtubule structure alterations as well as alterations of binding partners necessary for proper microtubule dynamics resulting from pathogenic variants in TUBA1A, TUBB2A, TUBB2B, TUBB3, TUBB5, TUBG1 and TUBA8 genes are also responsible microcephaly and microlissencephaly." (PMID 30340542, 2018).
developmental delay (5 papers, 2021 to 2025). "Most common, partially overlapping symptoms at disease onset in the TUBB2B cohort were developmental delay (47.4%), seizures (36.8%), and muscular hypotonia (21.1%)." (PMID 33082561, 2021). "Among these, dominant TUBB2B variants have been associated with cortical dysplasia, complex, with other brain malformations 7 (CDCBM7, MIM #610031), a condition characterized by a broad range of MCDs with developmental delay/intellectual disability (DD/ID) and seizures." (PMID 41153399, 2025). "In three patients with myoclonus as primary phenotype, mutation of TUBB2B (OMIM 610031), ATRX, or DHDDS (developmental delay and seizures with or without movement abnormalities; OMIM 617836) gene were found to be causative." (PMID 35719373, 2022).
neuroblastoma (5 papers, 2019 to 2025). Neuroblastoma (NB) is the most common solid, extracranial childhood tumor. "Upregulated TUBB2B in neuroblastoma and endometrial cancer is associated with poorer prognosis." (PMID 39962586, 2025). "TUBB2B is highly expressed and associated with poor OS in endometrial cancer and neuroblastoma." (PMID 36872411, 2023). "Upregulation of TUBB2B may contribute to the development of neuroblastoma." (PMID 33869220, 2021). "In the context of cancer, recent studies reported overexpression of TUBB2B in hepatocellular carcinoma (HCC), neuroblastoma, Hodgkin lymphoma and endocrine therapy-resistant breast cancer." (PMID 39962586, 2025). "TUBB2B and FGF12 have been suggested to play vital functions in prostate cancer, neuroblastoma, and esophageal squamous cell carcinoma; however, their roles in HBV-related GC development have never been documented and merit further investigations." (PMID 35592651, 2022).
brain malformations (4 papers, 2015 to 2025). "Heterozygous missense variants in TUBB2B are linked to cortical dysplasia, complex with other brain malformations (CDCBM7 [MIM:610031]) with variable molecular mechanisms of disease such as LOF, dominant negative, and gain of function." (PMID 41503485, 2025). "TUBB2B is associated with cortical dysplasia complex and brain malformations (CDCBM7 [MIM: 610031])." (PMID 41503485, 2025).